FPR2 (formyl peptide receptor 2)
Diseases named in the same sentence as FPR2 in open-access papers (continued):
Sharing a sentence is not in itself a finding about the gene and the disease.
E. coli infection (2 papers, 2021 to 2023). "Further study revealed that E. coli infection upregulated the expression of Fpr2 in colon epithelial cells." (PMID 37322488, 2023). "Studies assessing L. monocytogenes and E. coli infections demonstrated that Fpr2 is a direct chemotactic neutrophils factor during early immune responses." (PMID 34899755, 2021).
encephalitis (2 papers, 2022 to 2023). An acute inflammatory process affecting the brain parenchyma. "Furthermore, in HSV1 encephalitis in mice, the absence of AnxA1 or FPR2 was associated with reduced mortality and lower tissue viral loads compared to infected WT controls." (PMID 37190040, 2023). "We showed that blocking Anx-A1 or FPR2 decreases HSV-1 attachment to cells by 20 to 30% and ameliorates HSV-1-induced encephalitis in mice." (PMID 35939498, 2022).
epilepsy (2 papers, 2021 to 2022). A brain disorder characterized by episodes of abnormally increased neuronal discharge resulting in transient episodes of sensory or motor neurological dysfunction, or psychic dysfunction. "In summary, these results showed that the expression and specific distribution of FPR2 may be involved in epilepsy caused by FCDIIb and TSC, indicating that downregulation of FPR2 mediated the dysfunction of neuroinflammation resolution in FCDIIb and TSC." (PMID 36301030, 2022). "Moreover, it is unclear whether MCDs or epilepsy caused decreases in RvD1 and FPR2 expression or whether low RvD1 and FPR2 expression caused MCDs with epilepsy." (PMID 36301030, 2022). "To explore the potential roles of formyl peptide receptor 2 (FPR2), which is a key regulator of inflammation resolution, in epilepsy caused by FCDIIb and TSC, we examined the expression and cellular distribution of FPR2." (PMID 36301030, 2022). "The detailed cellular function and mechanism of FPR2 in epilepsy and the development of FCD and TSC need to be further researched to explore possible new directions for the control of MCDs and epilepsy caused by MCDs." (PMID 36301030, 2022). "The results indicate that FPR2 activation may be a potential strategy for attenuating seizures and for uniform progression of epilepsy in FCDIIb and TSC patients." (PMID 36301030, 2022). "Collectively, FPR2 and RvD1 expressions are involved in epilepsy in FCDIIb and TSC patients." (PMID 36301030, 2022). "FPR2 binds to AnxA1 to activate a series of signaling pathways, including intracellular calcium influx and activation of MAPKs, which contribute to synaptic excitability and cognitive impairment in the pathophysiology of epilepsy." (PMID 34650406, 2021).
fetal growth restriction (2 papers, 2020 to 2022). A fetus that does not grow beyond the 10th percentile of conventionally accepted weight for gestational age. "It was reported that FPR2 played an important role in fetal growth restriction (FGR)." (PMID 35018584, 2022).
HIV-1 infection (2 papers, 2008 to 2025). The type species of lentivirus and the etiologic agent of acquired immunodeficiency syndrome (AIDS). "Thus, the exact role of FPR2 during HIV-1 infections remains elusive." (PMID 40703440, 2025).
laryngeal carcinoma (2 papers, 2014 to 2025). Carcinoma that arises from the laryngeal epithelium. "Loss of ANXA1 and FPR2/ALX expression was detected in laryngeal carcinoma cells." (PMID 25490767, 2014). "In this report, we showed that ANXA1 protein is down-regulated in human laryngeal carcinoma and can regulate tumor growth in a paracrine manner that is mediated by the receptor FPR2/ALX." (PMID 25490767, 2014). "In the inflammatory cells of human laryngeal carcinoma tissue samples, ANXA1/FPR2 expression was markedly exacerbated; however, in laryngeal carcinoma cells, this expression was down-regulated." (PMID 25490767, 2014). "Overall, this study identified potential roles for the molecular mechanism of the ANXA1/FPR2 interaction in laryngeal cancer, including its relationship with the prostaglandin pathway, providing promising starting points for future research." (PMID 25490767, 2014). "In these inflammatory cells of peritumoral and tumor samples, ANXA1/FPR2 expression was markedly exacerbated, however, in laryngeal carcinoma cells, this expression was down-regulated." (PMID 25490767, 2014). "The tumor-activated inflammatory cells appear to increase the synthesis of ANXA1/FPR2 proteins as an anti-inflammatory response mechanism to resolve the inflammation and proliferation in laryngeal cancer." (PMID 25490767, 2014). "Our results established, for the first time, the role of FPR2/ALX in laryngeal carcinoma cells as demonstrated by ultrastructural analyses showing the co-localization of ANXA1/FPR2." (PMID 25490767, 2014). "Overall, our in vivo data indicated that mast cells and neutrophils, under activation by the tumor microenvironment, demonstrate up-regulation of ANXA1/FPR2 as an anti-inflammatory response mechanism to resolve inflammation and proliferation in laryngeal cancer." (PMID 25490767, 2014).
leishmaniasis (2 papers, 2019 to 2024). Infectious disease that is transmitted through the bite of hematophagous female phlebotomine sand flies. "Further, it is tempting to speculate that the therapeutic success FPR2 antagonists have displayed against influenza viruses in preclinical trials could be leveraged in the fight against leishmaniasis, although additional pre-clinical and clinical studies are required to assess their efficacy." (PMID 39076982, 2024).
leukemia (2 papers, 2012 to 2021). A malignant (clonal) hematologic disorder, involving hematopoietic stem cells and characterized by the presence of primitive or atypical myeloid or lymphoid cells in the bone marrow and the blood. "After removal of neutrophils by centrifugation, we stimulated human leukemia cells 60 overexpressing FPR2 (HL60-FPR2) with these culture filtrates and observed that pretreatment with neutrophils prevented FPR2 activation in a dose-dependent manner." (PMID 34552584, 2021).
myocardial ischemia (2 papers, 2018 to 2021). A disorder of cardiac function caused by insufficient blood flow to the muscle tissue of the heart. "ALX/FPR2 is also upregulated during myocardial ischemia, and its ligands limit myocardial necrosis and inflammation after coronary ligation." (PMID 30487747, 2018).
parasitemia (2 papers, 2021 to 2024). "Altogether, this suggests that the ANXA1/FPR2 interaction in myeloid cells is a key contributor to skin pathology and parasitemia during cutaneous leishmaniasis." (PMID 39076982, 2024). "In the experimental model used, the course of parasitemia in the WT and FPR2-/- mice was representative of the behavior expected by the Dm28c strain of T. cruzi." (PMID 34784372, 2021). "Specifically, parasitemia in the FPR2-/- mice was reduced after three weeks p.i., the time when an adaptive antigen-specific response is established and cytotoxic and helper T lymphocytes and B cells participate." (PMID 34784372, 2021). "Pre-treatment of wildtype C57BL/6 mice with the FPR2 antagonist WRW4 was capable of inhibiting LeishEXO-mediated immunopathogenesis, decreasing footpad swelling as well as parasitemia." (PMID 39076982, 2024). "The progression of parasitemia and mortality in C57BL/6 WT and FPR2-/- mice infected with T. cruzi strain Dm28c were determined to evaluate the establishment of a murine model for chronic CD." (PMID 34784372, 2021).
periodontitis (2 papers, 2022 to 2025). An acute or chronic inflammatory process that affects the tissues that surround and support the teeth. "The influence of annexin A1 (ANXA1)-mediated formylpeptide receptor-2 (FPR2) on periodontal pathology was studied in a rodent model of periodontitis and human periodontal ligament cells." (PMID 41002732, 2025). "In the present study, FPR2 was upregulated in neutrophils infiltrated in periodontal tissue during periodontitis and mainly attributed to pyroptosis." (PMID 36686646, 2022). "The scRNA sequencing data analysis revealed that among 21 DCDEGs, SLC2A3, FPR2, TREM1, and IL1B were mainly upregulated in neutrophils present in the periodontium of periodontitis patients." (PMID 36686646, 2022). "In conclusion, our study showed that SLC2A3, FPR2, TREM1, and IL1B mainly upregulated in neutrophils infiltrated in periodontium during periodontitis." (PMID 36686646, 2022). "We found that among 21 DCDEGs, SLC2A3, FPR2, TREM1, and IL1B were mainly upregulated in neutrophils present in the periodontium of periodontitis patients." (PMID 36686646, 2022). "This is the first bioinformatics report describing the upregulation of necroptosis (IL-1B), pyroptosis IL-1B, TREM1, and FPR2, and ferroptosis (SLC2A3) related genes mainly in human periodontium infiltrated neutrophils during periodontitis." (PMID 36686646, 2022). "The rigorous bioinformatics analysis performed in this study provided hints that SLC2A3, FPR2, TREM1, and IL1B are upregulated in neutrophils infiltrated in periodontium during periodontitis and mainly attributed to necroptosis, pyroptosis, and ferroptosis." (PMID 36686646, 2022). "Discussion: The findings provide upregulated SLC2A3, FPR2, TREM1, and IL1B in neutrophils as a future research direction on the mode and mechanism of cell death in periodontitis and their role in disease pathogenicity." (PMID 36686646, 2022).
pneumococcal meningitis (2 papers, 2020 to 2024). An acute purulent infection of the meninges and subarachnoid space caused by Streptococcus pneumoniae, most prevalent in children and adults over the age of 60. "Our own previous works in a mouse model of pneumococcal meningitis and liver injury after lipopolysaccharide inflammation as well suggest an anti-inflammatory role for FPR2." (PMID 33121515, 2020). "Moreover, a recent study showed that treatment with Ac2-26 reduced the inflammatory response following pneumococcal meningitis in an FPR2-dependent manner." (PMID 39768195, 2024). "Our earlier results demonstrated that the anti-inflammatory properties of Ac2-26 in a model of pneumococcal meningitis are mediated via FPR2 but not FPR1." (PMID 39768195, 2024).
preeclampsia (2 papers, 2022). Preeclampsia is a hypertensive disorder of pregnancy that is characterized by new-onset hypertension with proteinuria presenting after 20 weeks of gestation, and depending on mild or severe forms may initially present with severe headache, visual disturbances, and hyperreflexia. "According to a related report, significantly higher levels of FPR2 were observed in umbilical cord blood and placenta obtained from pregnant women with preeclampsia." (PMID 36142517, 2022). "This present study aimed to explore the effect of FPR2 on a trophoblast cellular model of preeclampsia." (PMID 35018584, 2022).
retinal degeneration (2 papers, 2022 to 2024). Degeneration of the retina. "This study showed that retinal inflammation from activated microglia and dysregulation of lipid metabolism were central to the pathogenesis of retinal degeneration in RP, where ALXR/FPR2 activation was able to preserve retinal structure and function." (PMID 38396985, 2024). "Indeed, in RD1 mice, a model of rapid retinal degeneration, LXA4 byosintesis (5-LOX and 15-LOX) and receptor (ALX/FPR2) resulted in markedly downregulated in end-stage RD1 retinas." (PMID 35562891, 2022).
skin infection (2 papers, 2020 to 2023). An inflammatory process affecting the skin, caused by bacteria, viruses, parasites, or fungi. "Activation of FPR2 by PSMα peptides leads to cytokine release, neutrophil chemotaxis and activation during Staphylococcus aureus skin infections." (PMID 32983167, 2020). "Neutrophils also express FPR2 and play a crucial role during skin infection." (PMID 37325619, 2023).
staphylococcal infection (2 papers, 2012 to 2013). An infection caused by Staphylococcus. "Two synthetic PSM peptides utilize FPR2 in neutrophils to produce reactive oxygen species, which in turn trigger inactivation of the peptides, suggesting that FPR2 is crucial in staphylococcal infections and may represent an attractive target for new anti-infective or anti-inflammatory strategies." (PMID 23549262, 2013).
subarachnoid haemorrhage (2 papers, 2018 to 2022). "LXA4 has been shown to improve learning and memory after subarachnoid haemorrhage, and these effects were mediated by FPR2." (PMID 29948727, 2018).
ulcerative colitis (2 papers, 2018 to 2025). An inflammatory bowel disease involving the mucosal surface of the large intestine and rectum. "The activation of FPR2 using selective agonists has been shown to induce therapeutic effects for several infectious- or inflammatory diseases such as polymicrobial sepsis, ulcerative colitis, and certain cancers." (PMID 30279454, 2018).
uveitis (2 papers, 2023 to 2024). An inflammatory process affecting a part of or the entire uvea. "In addition, previous studies reported that ANXA1 (Ac2-26) inhibits inflammatory responses through Fpr2 in LPS-induced uveitis in rats." (PMID 36544058, 2023). "RvD1 is a ligand for ALXR/FPR2, and its effects have been shown in an endotoxin-induced uveitis rat model where direct IVT administration of RvD1 improved clinical scores and reduced TNF-α and NF-κB activation." (PMID 38396985, 2024).
acute lung injury (1 paper, 2020). A condition of lung damage that is characterized by bilateral pulmonary infiltrates (pulmonary edema) rich in neutrophils, and in the absence of clinical heart failure. "As receptor, FPR2 displays potent mucosal protection and promotes catabasis after acute lung injury (ALI), providing a novel therapeutic target to develop an effective treatment against ALI progression." (PMID 32983259, 2020).
acute pancreatitis (1 paper, 2020). An acute inflammatory process that leads to necrosis of the pancreatic parenchyma. "Another ALX/FPR2 agonist, RvD1, proved beneficial in restoring autophagic flux in a mouse model of cerulein-induced acute pancreatitis (AP), where autophagy plays a clear role in supporting inflammation." (PMID 32927853, 2020).
allergic conjunctivitis (1 paper, 2021). "In contrast, intense expression of both fprs were detected in conjunctival epithelial cells in an allergic conjunctivitis model, but the lack of AnxA1 protein in the ovalbumin-sensitized mice produced a marked increase only in fpr2 expression." (PMID 34831393, 2021).
aortic aneurysm (1 paper, 2024). A ruptured aneurysm located in the wall of the proximal portion of the descending aorta proceeding from the arch of the aorta. "Importantly, aortic aneurysm inflammation was increased in formyl peptide receptor 2 (FPR2) receptor-deficient mice, thus demonstrating RvD1/FPR2-dependent signaling." (PMID 38921449, 2024).
atopic dermatitis (1 paper, 2023). "On the contrary, in patients with atopic dermatitis, inhibition of FPR2 in keratinocytes promotes chronic S. aureus colonization." (PMID 37325619, 2023). "Since S. aureus skin colonization and subsequent skin inflammation plays a crucial role in atopic dermatitis, we analyzed the influence of FPR2 on S. aureus colonization in an in vivo model that simulates human atopic dermatitis." (PMID 37325619, 2023).
atrial fibrillation (1 paper, 2021). A disorder characterized by an electrocardiographic finding of a supraventricular arrhythmia characterized by the replacement of consistent P waves by rapid oscillations or fibrillatory waves that vary in size, shape and timing and are accompanied by an irregular ventricular response. "And bioinformatics analysis of upregulated genes indicates that pathway endodermal cell differentiation and key genes EGFR, GNG2, and FPR2 are related to atrial fibrillation." (PMID 34938350, 2021). "The protein-protein interaction network revealed that EGFR, GNG2, and FPR2 were related to atrial fibrillation." (PMID 34938350, 2021). "We could conclude that EGFR, GNG2, and FPR2 were the most closely related to patients with atrial fibrillation." (PMID 34938350, 2021). "The PPI network analysis illustrated that the hub genes related to atrial fibrillation are EGFR, GNG2, and FPR2." (PMID 34938350, 2021).
bacterial pneumonia (1 paper, 2020). Acute infection of the lung parenchyma caused by bacteria (e.g., Streptococcus pneumoniae, Haemophilus influenzae, Chlamydia pneumoniae, Mycoplasma pneumoniae, and Legionella pneumophila). "Although PSMs do not lyse cells at submicromolar concentrations, they can trigger an inflammatory host response in neutrophils by interacting with the formyl peptide receptor 2 (FPR2) thereby contributing to the destructive inflammatory response characteristic of bacterial pneumonia." (PMID 33218049, 2020).
brain inflammation (1 paper, 2020). "Several studies demonstrated that Fpr1- and/or Fpr2-deficient mice are protected from neuronal pathologies, among studies to experimental demyelination or lipopolysaccharide-induced brain inflammation." (PMID 33121515, 2020).
brain tumors (1 paper, 2023). "Although the presence of FPR2 in the brain and its involvement in the inflammatory response and regulation of neuronal function have been established, the expression of this formylpeptide receptor in brain tumors has been described to a limited extent." (PMID 37627089, 2023).
breast tumors (1 paper, 2020). "While the expression of the HN trimeric receptor subunits was similar in all subtypes of breast tumors, the expression of FPR2 differs with tumor type, being highest in TNBC." (PMID 32444831, 2020). "In fact, our analysis of transcriptomic data from breast tumor specimens indicates that HN receptors are present in breast tumors of all types, and that FPR2 expression is highest in TNBC." (PMID 32444831, 2020).
cardiac hypertrophy (1 paper, 2021). "It is important to note that Bz alone did not affect cardiac hypertrophy; however, when combined with AT-RvD1, it significantly reduced the cross-sectional area of cardiomyocytes in the WT mice, but not in the absence of FPR2." (PMID 34784372, 2021). "Although AT-RvD1 significantly reduced cardiomyocyte cross-sectional area, the effect was blunted by the absence of FPR2 because in the FPR2-/- mice, there was no reduction in cardiac hypertrophy." (PMID 34784372, 2021).
cardiomyopathy (1 paper, 2023). A disease of the heart muscle or myocardium proper. "Fpr2 dysfunction magnified obesogenic cardiomyopathy and neutrophil recruitment in aging mice." (PMID 36776849, 2023).
cerebral thrombosis (1 paper, 2025). "Since targeting the AnxA1/FPR2 pathway can inhibit thromboinflammation and cerebral thrombosis, it is plausible that FPR2 and ANXA1 participate in thrombus evolution." (PMID 41464211, 2025).
colorectal adenocarcinoma (1 paper, 2013). The most common type of colorectal carcinoma. "In breast epithelial tumor cells, the signaling elicited by ANXA1/FPR2 interaction induces an increased level of cyclin D1, which is associated to the activation of the PI3K/Akt/p70S6K pathway, and in SKCO-15 colorectal adenocarcinoma, ANXA1 mediates cell invasion via FPR2." (PMID 23549262, 2013).
colorectal tumor (1 paper, 2017). "In this work, we found that the expression of FPR1, but not FPR2 or FPR3, was associated with colorectal tumor serosal invasion." (PMID 28724995, 2017).
cutaneous leishmaniasis (1 paper, 2024). Leishmaniasis affecting the skin. "As FPR2 is an established downstream receptor of ANXA1, we aimed to assess the implication of the ANXA1/FPR2 receptor-ligand interaction in an in vivo model of experimental cutaneous leishmaniasis." (PMID 39076982, 2024).